HOTAIR (HOX transcript antisense RNA)
Diseases named in the same sentence as HOTAIR in open-access papers (continued):
Sharing a sentence is not in itself a finding about the gene and the disease.
tumor (continued). "Elevations in the expression and hyperactivation of HOTAIR, and the consequent retargeting of PRC2 and LSD1-REST-coREST1 are thought to be associated with dysregulated epigenetic statuses of underlying genes and aggravation of tumor cell invasiveness and metastases." (PMID 38366205, 2024). "We speculated that HOTAIR could be a promising tumor marker for detecting HCC." (PMID 39128100, 2024). "Furthermore, in line with evidence reported for other lncRNAs, HOTAIR can participate in intercellular communication being itself embedded in EVs, particularly exosomes secreted by different tumor cells, thus representing a circulating marker of disease progression." (PMID 37308974, 2023). "In addition, a study involving CRC patients showed that exosomal HOTAIR is positively correlated with infiltration of PDL1+ B cells in tumor tissues, suggesting that exosomal therapy targeting HOTAIR may be a new therapeutic strategy for CRC." (PMID 37553810, 2023). "Therefore, HOTAIR can be used as a candidate target for inhibiting the tumor cell cycle evolution." (PMID 35813070, 2022). "HOTAIR expression could also be induced by the tumor microenvironment such as hypoxia." (PMID 36494673, 2022). "Therefore, HOTAIR has been regarded as a new tumor marker of HCC." (PMID 35093153, 2022). "Additionally, interference of HOTAIR had impacted BC tumor growth in vivo." (PMID 36387279, 2022). "Similarly, lncRNA HOTAIR led to tumor metastasis by reprograming the chromatin state, which suggested that lncRNAs possess the potential to become important targets of tumor diagnosis and treatment for their active role in regulating the tumor epigenome." (PMID 36059686, 2022). "Furthermore, we used a targeted approach based on the data from GC tumor tissues, but in future studies, a multiomics approach may provide additional insight into the concomitant changes related to HOTAIR expression." (PMID 35347094, 2022). "Moreover, HOTAIR overexpression dramatically enhanced xenograft tumor growth." (PMID 36273585, 2022). "In addition, overexpressed HOTAIR reduced the sensitivity of tumor cells to chemoradiotherapy." (PMID 34367966, 2021). "Therefore, various lncRNAs such as H19 and HOTAIR can also be used as markers of tumor recurrence." (PMID 31956395, 2020). "Therefore, our research suggested that HOTAIR might function as a tumor promoter in the progression of BC." (PMID 32694942, 2020). "Finally, tumour growth was assessed to determine the effects of HOTAIR/miR‐206/STC2 axis in vivo." (PMID 31297902, 2019). "Thus, HOTAIR expressed by tumor cells could positively regulate MDSC generation in vitro; nevertheless, the associated molecular mechanisms have not been determined." (PMID 31404149, 2019). "Hence, HOTAIR expression could exert a more generalized function by promoting inflammation and immunosuppression within the tumor microenvironment." (PMID 31404149, 2019). "HOTAIR, through interaction with microenvironment elements, could play a main role in the activation of specific growth and invasion molecular pathways, and in the regulation of immune response during tumor progression." (PMID 31072041, 2019). "As one of the regulators of oncogene transcription, HOTAIR remodels PRC2 and desmethylase LSD1 complexes by recruiting chromatin to cause demethylation of Histone H3K27em3, silence of HOXD gene expression, ultimately facilitate tumor proliferation or metastasis at the epigenetic level." (PMID 29463216, 2018). "Thus, an increase in HOTAIR expression may be a potential biomarker for tumor progression and evaluation of prognosis." (PMID 28591050, 2017). "The biological role of HOTAIR in tumor cells may mediate the poor CC outcome." (PMID 29108287, 2017). "Therefore, HOTAIR not only exhibits oncogenic activity but also indicates poor tumor prognosis." (PMID 29299179, 2017).
tumor (continued). "Results support Notch1′s putative tumour progression function, but there is little evidence of associated downstream factors that contribute to the regulation of these processes associated with HOTAIR." (PMID 27323817, 2016). "However, we found no further association between increased HOTAIR expression and tumor stage due to the small cohort size of this sample set." (PMID 25994132, 2015). "HOTAIR, seems to be an indicator of poor prognosis in GC patients, since its overexpression was associated with advanced TNM and pathological stage, large tumor size, increased tumor invasiveness, and metastatic potential as well as with an adverse outcome in terms of OS." (PMID 26064090, 2015). "To determine whether the tumor-suppressive effects of HOTAIR knockdown were mediated by miR-326, we transfected miR-326 mimics or miR-326 inhibitors into the stable sh-HOTAIR cells prior to the assessment of cell proliferation, apoptosis, migration, invasion and cell cycle." (PMID 26183397, 2015). "Therefore, HOTAIR may promote tumor aggressiveness through the upregulation of VEGF and MMP-9 and EMT-related genes." (PMID 25405331, 2015). "However, whether FGF1 was involved in the tumor-suppressive effects of HOTAIR knockdown needed to be further studied." (PMID 26183397, 2015). "In this context, we have recently shown that EZH2 mediates recurrence in NMIBC, being also upregulated in tumor samples and especially in recurrent tumors.The current study gives an insight into the regulation of HOTAIR, indicating that EZH2 may regulate HOTAIR expression." (PMID 26457124, 2015). "Moreover, HOTAIR overexpression-either in tumor tissue or in blood-may identify patients that would require more intensive care of personally tailored treatment." (PMID 25334066, 2014). "Our data suggest that HOTAIR may be frequently upregulated in many tumor cells." (PMID 24775712, 2014). "In CC, numerous lncRNAs (e.g., HOTAIR, MALAT1) and miRNAs (e.g., miR-21, miR-34a) have been validated as oncogenes or tumor suppressors, regulating tumor progression and microenvironment remodeling through complex ceRNA networks." (PMID 41614894, 2026). "Tumor-suppressive miRNAs, such as miR-125b and miR-509-5p, are sequestered by long non-coding RNAs (lncRNAs), like MALAT1 and HOTAIR, which act as competing endogenous RNAs (ceRNAs), enhancing oncogenic signaling." (PMID 41596492, 2026). "In NSCLC, HOTAIR negatively regulates the chemokine CCL22, thus inhibiting T cell immune activity in the tumor microenvironment, while promoting cell proliferation, migration, and invasion." (PMID 40723840, 2025). "HOTAIR interacts with the polycomb repressive complex 2 (PRC2) to silence tumor suppressor genes and promote tumor growth and metastasis." (PMID 41011238, 2025). "Studies have demonstrated that FOXC2 can regulate HOTAIR, an oncogenic lncRNA that recruits Polycomb Repressive Complex 2 (PRC2) to silence tumor suppressor genes, facilitating metastasis and EMT activation." (PMID 40781106, 2025). "For example, STAT3 binds to the promoter region of the HOTAIR gene, enhancing its expression and thereby promoting EZH2‐mediated silencing of tumor suppressor genes in HNSCC." (PMID 40231344, 2025). "While several studies have identified roles of HOTAIR, UCA1, and MALAT1 in tumor progression, the transcriptional control of these lncRNAs by BCSC-associated factors remains only partially elucidated." (PMID 40781106, 2025). "HOTAIR is highly expressed in OSCC and the level of expression is correlated with tumor lymph node metastasis stage, histological grade, and regional lymph node metastasis." (PMID 40231344, 2025). "Specifically, HOTAIR has been shown to be highly expressed in OSCC, enhancing the metastatic potential of tumor cells and the expression of EMT markers." (PMID 41020820, 2025). "lncRNAs, such as HOTAIR and MALAT1, upregulate BCL-2 via epigenetic and ceRNA mechanisms, promoting tumor survival." (PMID 41020820, 2025).
tumor (continued). "Simultaneously, HPV upregulates oncogenic long non-coding RNA (lncRNAs) such as HOTAIR and MALAT1, which modulate chromatin modifiers and sponge tumor-suppressive miRNAs, reinforcing oncogenic signaling (Castro-Oropeza and Piña-Sánchez, 2022)." (PMID 40557320, 2025). "LncRNA MALAT1 and HOTAIR are highly expressed in LUAD, promoting tumor cell proliferation, and inhibiting apoptosis by regulating cell cycle proteins and apoptosis-related molecules (such as BCL-2 and BAX)." (PMID 39834603, 2025). "HOTAIR interacts with EZH2 to recruit the PRC2 complex, which catalyzes H3K27me3, thereby repressing the expression of tumor suppressor genes." (PMID 41353219, 2025). "LINC01133, like other lncRNAs of interest, such as HOTAIR, MALAT1, TUG1, and FOXCUT, should be at the forefront of clinical research, considering its importance both in the intratumoral context and in the tumor microenvironment." (PMID 40863724, 2025). "HOTAIR, which is overexpressed in TNBC, promotes tumor growth and metastasis by silencing tumor suppressor genes and activating oncogenic pathways." (PMID 41011238, 2025). "For example, the interaction between HOTAIR and the PRC2 complex is known to promote metastasis by silencing tumor suppressor genes." (PMID 40861865, 2025). "LncRNAs like HOTAIR and MALAT1 interact with the Notch signaling pathway to promote tumor cell proliferation, metastasis, and drug resistance." (PMID 40621472, 2025). "In our previous studies, we found that AQB, a small molecule drug targeting HOTAIR and EZH2, restores the expression of multiple tumor suppressor genes and inhibits EC progression, demonstrating significant antitumor activity and a favorable safety profile." (PMID 41353219, 2025). "It has been previously demonstrated to inhibit the progression of EC by disrupting the interaction between HOTAIR and EZH2, thus restoring the expression of multiple tumor suppressor genes." (PMID 41353219, 2025). "In UCEC, HOTAIR has been reported to accelerate the EMT process by reducing E-cadherin levels, thereby enhancing the invasive capacity of tumor cells." (PMID 40001977, 2025). "HOTAIR recruits the PRC2 complex, leading to epigenetic silencing of tumour-suppressor genes (e.g., PTEN) and subsequent upregulation of VEGF." (PMID 41463281, 2025). "A similar case can be seen in the lncRNA HOTAIR, which is also an AR‐repressed gene that prevents AR protein from undergoing ubiquitin‐mediated degradation in CRPC tumours but avoids being repressed." (PMID 38214432, 2024). "Further experiments suggested that HOTAIR regulated matrix metalloproteinases and EMT-related genes, facilitating migration and invasion of cell lines and promoting intraperitoneal tumor growth and metastasis in nude mice." (PMID 38725621, 2024). "The present study demonstrated that HOTAIR was overexpressed in CRC tumor tissues, especially in radioresistant tumor samples." (PMID 39055884, 2024). "In vitro experiments with PTC cells revealed that HOTAIR promotes EMT, which is crucial for migration, invasion, and acquisition of stemness in PTC tumor cells through modulation of the Wnt/Catenin signaling pathway." (PMID 38339237, 2024). "LncRNAs, such as HOTAIR, PCGEM1, H19, and UCA1, are dysregulated in many types of tumor tissues and can function either as oncogenes or tumor suppressors through regulating cancer cell growth, apoptosis, and invasion." (PMID 38195623, 2024). "According to the 2021 review, anoikis-related lncRNAs including ANRIL, FOXD2-AS1, HOTAIR, and SNHG12 have been unveiled to participate in the process of tumor metastasis, stem cell formation and tumor survival." (PMID 38385949, 2024). "HOTAIR was significantly upregulated in CRC tumor tissues, especially in radioresistant tumor samples." (PMID 39055884, 2024).
tumor (continued). "Mechanistically, HOTAIR upregulated the metabolic enzymes UPP1 by recruiting histone methyltransferase EZH2, thereby increasing the tumor progression." (PMID 38696320, 2024). "Acting as a molecular scaffold, HOTAIR bridges PRC2 and LSD1/CoREST/REST complexes and recruits them to the promoter regions of distant tumor suppressor and metastasis suppressor genes." (PMID 38339237, 2024). "The expression profile for both HOTAIR and AFAP1‐AS1 revealed that their expression was higher in tumor tissue compared to normal tissue, although only AFAP1‐AS1 in LUSD had a statistically significant difference." (PMID 39725668, 2024). "HOTAIR is misregulated in several types of cancers and contributes to proliferation, epithelial-mesenchymal transition (EMT), tumor migration, and invasion." (PMID 39795985, 2024). "Operating as an oncogene, HOTAIR recruits EZH2 to catalyze the trimethylation of histone H3 at lysine 27 (H3K27me3), thereby repressing downstream tumor suppressor genes." (PMID 38522008, 2024). "Functionally akin to HOTAIR, ANRIL suppresses the activity of the p15 INK4B gene, a crucial tumor suppressor involved in cell cycle regulation, senescence, and stress-mediated apoptosis." (PMID 38329598, 2024). "In CRC, HOTAIR upregulated the metabolic enzymes UPP1 by recruiting EZH2, thereby promoting the tumor progression, suggesting a novel metabolic axis for CRC therapy." (PMID 38696320, 2024). "The interaction of HOTAIR with miR-122 via EZH2-mediated DNA methylation is a unique mechanism of lncRNA–miRNA interaction, contributing to gene regulation in tumor cells." (PMID 37345170, 2023). "This study demonstrated that HOTAIR levels are considerably higher in stage II, III, and IV tumor tissue samples than in stage I samples." (PMID 36997931, 2023). "HOTAIR down-regulates Mir-130a-3p and reduces its binding to its target gene ATG2B, thereby affecting tumor chemosensitivity." (PMID 36924407, 2023). "Using an orthotopic mouse model, this study proved that the silencing of HOTAIR provokes the lung metastasis of TNBC cells and tumor growth." (PMID 36997931, 2023). "HOTAIR is a lncRNA also involved in tumor cell growth, with additional implications for TME maintenance and increased tumor resistance to chemotherapies." (PMID 37174089, 2023). "Tang et al26 found that MALAT‐1 and HOTAIR are expressed in patients with primary OSCC tumors; the expression level of HOTAIR differed between patients with LNM and primary tumor controls." (PMID 37635388, 2023). "For instance, the knockdown of HOTAIR by siRNA can reduce proliferation, migration, and invasion of human HCC cells and inhibit tumor growth in an HCC mouse xenograft model." (PMID 37240232, 2023). "In HeLa and C33A cells with high HOTAIR expression, HIF-1α expression can be increased after radiotherapy, leading to radiation resistance and tumor growth, but this effect can be neutralized by miR-217 mimics." (PMID 37692844, 2023). "Like NSCLC, the downregulation of HOTAIR also induced chemosensitivity in SCLC by increasing cellular apoptosis and suppressing tumor development in vivo." (PMID 36778005, 2023). "Besides its important role in tumorigenesis, the latest report suggest that the high expression level of HOTAIR in HCC is associated with disease progression, could be a candidate biomarker for predicting tumor recurrence in HCC patients and might be a potential therapeutic target." (PMID 37171645, 2023). "The results showed that HOTAIR targets the JAK/STAT signaling pathway, a mitochondria-dependent signaling pathway involving Bcl-2 and Bax, to interfere with tumor growth and apoptosis." (PMID 36924407, 2023).
tumor (continued). "The high expression of lncRNA HOTAIR in epithelial cancer can promote cellular EMT, metastasis, and CSC formation, and is positively related to the poor prognosis of tumor patients." (PMID 38070058, 2023). "RT-qPCR results illustrated higher expression of HOTAIR and EVA1 and lower miR-526b-3p level in tumor tissues of mice injected with U251 cells co-cultured with GBM-serum-EVs." (PMID 35418162, 2022). "In breast cancer, HOTAIR is overexpressed and interacts with PRC2 to induce the repressive histone methylation, which suppresses the expressions of several tumor-suppressor genes, thereby resulting in tumor invasion and metastasis." (PMID 36010595, 2022). "An increase in HOTAIR was also detected in NSCLC and paralleled by a decrease in miR-34a-5p, a tumor suppressor miRNA." (PMID 35984196, 2022). "Tumor-initiating formation was then determined by a limiting dilution injection of these CSCs into NOD/SCID nude mice, and the result showed that HOTAIR overexpression resulted in a much stronger tumor presence." (PMID 36273585, 2022). "LncRNAs regulate EMT process by targeting EMT-related signalling pathways directly (i.e., H19, HOTAIR, ZEB2-AS1, LincRNA-p21 and SNHG1), or function as ceRNAs (i.e., H19, HOTTIP, MALAT1, SNHG1 and SNHG6) for tumour suppressive miRNAs." (PMID 36310592, 2022). "As example, CASC2, TSLC1-AS1, and ADAMTS9-AS2 are tumor suppressor lncRNAs, while linc-POU3F3, HOTAIR, and H19 function to promote GBM cell cycle progression." (PMID 35668225, 2022). "HOTAIR expression has been shown to be high in CRC cell lines, tumor samples, and metastatic samples." (PMID 36010859, 2022). "Our data suggest that HOTAIR-mediated NF-κB signaling primes breast CSC self-renewal and tumor propagation." (PMID 36273585, 2022). "LncRNA such as HOTAIR, MEG2 can also affect tumor cell survival by affecting the expression of proteins related to mitochondrial apoptosis pathway." (PMID 35387966, 2022). "HOTAIR is an oncogenic long intergenic non-coding transcript (lincRNA) that is highly expressed in CRC and multiple other tumor types." (PMID 36010859, 2022). "In summary, HOTAIR can promote BCSC self-renewal and tumor propagation through activation of NF-κB signaling by recruiting the PRC2 complex to the IκBα promoter." (PMID 36273585, 2022). "HOTAIR targets miR-34a and activates the PI3K/AKT pathway and leads to tumor progression by inhibiting apoptosis." (PMID 35347094, 2022). "For example: HOTAIR, PVT1, H19 and MALAT1 showed oncogenic effect, while MEG3 and GAS5 have tumor suppressor effect." (PMID 35668225, 2022). "Our bioinformatics data illustrated that lncRNAs PART1, UCA1, DIRC3, HOTAIR, and HOXA11AS have more differential expression in the tumor tissues versus normal counterpart margins." (PMID 35949302, 2022). "There were trends towards increased expression of HOTAIR and EGFR in tumor tissues compared to adjacent normal tissues." (PMID 36471329, 2022). "In breast cancer, a variety of non-coding RNAs have been found to work as tumor suppressors or tumor-promoting effectors, such as XIST, HOTAIR, GAS5, MALAT1, etc.." (PMID 36230738, 2022). "HIF-1α can upregulate HOTAIR, NEAT1, UCA1, MALAT1, H19, and LincROR in tumor cells by specifically binding to the HREs of their promoter." (PMID 35387966, 2022). "There are two major categories of lncRs, which are defined as oncogenic lncRs such as MALAT1, HOTAIR, SOX2-OT and H19, and tumor suppressing lncRs such as MEG3, PANDAR, GAS5, and TUG1 according to their pathological features." (PMID 36552560, 2022). "Many other studies also described the contribution of HOTAIR to tumor microenvironment (TME) intracellular signaling, especially to tumor phenotype modifications during metastatic evolution." (PMID 33540611, 2021). "HOTAIR expression promotes the secretion of cytokines or chemical factors such as CCL2, which in turn induces tumor growth and metastasis." (PMID 35011565, 2021).